SPTBN1 (spectrin beta, non-erythrocytic 1)
Description:
Fodrin, which seems to be involved in secretion, interacts with calmodulin in a calcium-dependent manner and is thus candidate for the calcium-dependent movement of the cytoskeleton at the membrane. Plays a critical role in central nervous system development and function.
Synonyms: SPTB2; DDISBA; ELF; HEL102; betaSpII
Tractability: Antibody: UniProt places it where antibodies can reach, with high confidence; its Gene Ontology location is reachable by antibodies, with high confidence. PROTAC: ubiquitination databases record sites on it; its protein half-life has been measured.
Gene: Protein-coding gene on chromosome 2 (54,456,288 to 54,671,446, forward strand). Ensembl gene ENSG00000115306.
Subcellular location: Cytoplasm, cytoskeleton; Cytoplasm, myofibril, sarcomere, M line; Cytoplasm, cytosol; Cell membrane; Cell membrane (Isoform 2)
Subcellular location (Human Protein Atlas): Cytosol
Pathways (Reactome):
Signal Transduction: RAF/MAP kinase cascade; RHOU GTPase cycle; RHOV GTPase cycle
Developmental Biology: Interaction between L1 and Ankyrins; NCAM signaling for neurite out-growth
Sensory Perception: Sensory processing of sound by inner hair cells of the cochlea; Sensory processing of sound by outer hair cells of the cochlea
Cell-Cell communication: Nephrin family interactions
Disease: Signaling by FLT3 fusion proteins
Vesicle-mediated transport: COPI-mediated anterograde transport
Gene Ontology:
Molecular function: ankyrin binding; cadherin binding; GTPase binding; protein binding; RNA binding; structural constituent of cytoskeleton; actin binding; actin filament binding; phospholipid binding; protein-containing complex binding
Biological process: actin cytoskeleton organization; central nervous system development; central nervous system formation; Golgi to plasma membrane protein transport; membrane assembly; mitotic cytokinesis; plasma membrane organization; positive regulation of interleukin-2 production; positive regulation of protein localization to plasma membrane; protein localization to plasma membrane; regulation of protein localization to plasma membrane; vesicle-mediated transport
Cellular component: cytoplasm; cytosol; extracellular exosome; nucleolus; plasma membrane; axolemma; cell junction; cortical actin cytoskeleton; spectrin; spectrin-associated cytoskeleton; cortical cytoskeleton; cuticular plate; cytoskeleton; glutamatergic synapse; M band; membrane; nucleus; postsynapse; postsynaptic density; protein-containing complex
Genetic constraint (gnomAD): Loss-of-function variants: 32 observed, 271.12 expected, observed/expected ratio (o/e) 0.12, 90% interval 0.088 to 0.16. The upper end of that interval is the gene's LOEUF score, 0.16, which puts it in group 1 of 6, group 1 being the genes least tolerant of losing a copy. Missense variants: 2,293 observed, 3,208.7 expected, observed/expected ratio (o/e) 0.71, 90% interval 0.69 to 0.74. Synonymous variants: 1,335 observed, 1,223.4 expected, observed/expected ratio (o/e) 1.09, 90% interval 1.04 to 1.14.
Gene-disease validity (ClinGen):
ClinGen rates the evidence that SPTBN1 causes each of these diseases.
developmental delay, impaired speech, and behavioral abnormalities (autosomal dominant): Definitive.
Homologues: Orthologues: chimpanzee SPTBN1 (99% identical), macaque SPTBN1 (99% identical), dog SPTBN1 (99% identical), guinea pig SPTBN1 (99% identical), pig SPTBN1 (99% identical), mouse Sptbn1 (98% identical), rat Sptbn1 (98% identical), tropical clawed frog sptbn1 (91% identical), rabbit SPTBN1 (90% identical), zebrafish sptbn1 (84% identical), Drosophila melanogaster beta-Spec (55% identical), zebrafish sptbn1 (7% identical). Paralogues in human: SPTBN2 (63% identical), SPTB (59% identical), SPTBN4 (51% identical), DST (24% identical), MACF1 (24% identical), SPTBN5 (24% identical), SYNE1 (24% identical), SYNE2 (22% identical), SPTAN1 (19% identical), PLEC (18% identical), DMD (18% identical), UTRN (17% identical), and 24 more.
Diseases named in the same sentence as SPTBN1 in open-access papers:
SPTBN1 is named in the same sentence as 89 diseases in open-access papers, as found by Europe PMC text mining. Sharing a sentence is not in itself a finding about the gene and the disease. The quoted sentences say what the papers report.
hepatocellular carcinoma (26 papers, 2015 to 2026). A malignant tumor that arises from hepatocytes. "Studies have emphasized the effect and mechanism of tumor cell SPTBN1 on polarization and migration of tumor-associated macrophages in hepatoma and breast cancer, where its role is tightly linked to the biological behavior of tumors." (PMID 40321316, 2025). "SPTBN1 loss suppresses autophagy by modulating Yes‐associated protein (YAP) methylation in liver cell carcinoma, indicating a positive association between SPTBN1 and autophagy." (PMID 37679886, 2023). "Within the liver, the loss or downregulation of SPTBN1 expression promotes hepatocellular carcinoma—and other tumor progression—by interrupting the TGF-β pathway and enhancing the Wnt signaling pathway in mice and humans." (PMID 34829855, 2021). "A recent report showed that by regulating the Wnt inhibitor kallistatin, loss of SPTBN1 activates Wnt signaling and promotes progression of hepatocellular carcinoma and Wnt signaling." (PMID 27469031, 2016). "In hepatocellular carcinoma (HCC), hepatocellular carcinoma-effectively-associated tsRNA (HCETSR) derived from tRNA-Glu/TTC effectively suppresses malignant progression by regulating the SPTBN1/catenin axis, emerging as a promising prognostic biomarker and therapeutic target for HCC." (PMID 41550494, 2026). "Since SPTBN1 has also been shown to carry genetic alterations in hepatocellular carcinoma patients with a short OS, this may be a starting point for future investigations on SPTBN1 mutations in PDAC patients." (PMID 32860207, 2020). "Loss-of-function of SPTBN1 promoted hepatoma cell proliferation and migration." (PMID 27469031, 2016). "Mice heterozygous for Sptbn1, encoding the multifunctional Smad3 adaptor protein βII-spectrin (β2SP), alone or when combined with the heterozygosity of Smad3 (Sptbn1+/−, Smad3+/−Sptbn1+/−) spontaneously develop GI cancers and hepatocellular cancer (HCC) in the C57BL/6J background." (PMID 38323119, 2024). "In cancer, particularly hepatocellular carcinoma (HCC), high SPTBN1 expression is associated with poor prognosis, positioning it as a potential biomarker and therapeutic target." (PMID 40301996, 2025). "For instance, HCETSR (tRNA-Glu/TTC-derived) suppresses hepatocellular carcinoma via the SPTBN1/catenin axis, whereas tRF-23-Q99P9P9NDD promotes gastric cancer progression by modulating lipid metabolism and ferroptosis." (PMID 40565315, 2025). "Accordingly, in hepatocellular carcinoma, it was reported that the inhibition of SPTBN1 mediates β-catenin nuclear translocation, which was correlated with a less differentiated state of the tumor cells." (PMID 38069214, 2023). "The inhibition of SPTBN1 in hepatocellular carcinoma cells increases the expression of stem cell markers, and this process is consistent with the less differentiated nature of these two types of cells." (PMID 35706505, 2022). "As a cytoskeletal protein that maintains cell morphology and normal physiological functions, SPTBN1 is also involved in the malignant biological behavior of a variety of tumors, such as hepatocellular carcinoma, colorectal cancer, and pancreatic cancer." (PMID 32516133, 2020). "Dysfunction of the TGF-β–regulated SPTBN1/SMAD3/CTCF complex increases stem cell–like properties in hepatocellular carcinoma (HCC) cells and enhances tumorigenesis in tumor-initiating cells in a mouse model." (PMID 33457451, 2020). "SPTBN1 has emerged as a potent regulator of tumorigenesis as mice haploinsufficient for β2SP (Sptbn1+/−) spontaneously develop hepatocellular carcinoma HCC." (PMID 27248179, 2016). "HCETSR (tRNA-Glu/TTC-derived) suppresses hepatocellular carcinoma via the SPTBN1/catenin axis." (PMID 40565315, 2025). "As well, SPTBN1 hindered β-catenin’s nuclear translocation in hepatocellular carcinoma." (PMID 38069214, 2023).
hepatocellular carcinoma (continued). "Pathological indication of hepatocellular carcinoma formation and degradation or collapse of reticular fibers could be observed in the livers from Sptbn1+/- mice treated with DDC-containing diet." (PMID 33754058, 2021). "The role of SPTBN1 has been reported in multiple tumors, such as ovarian carcinoma, hepatocellular carcinoma (HCC), and kidney tumors." (PMID 38069214, 2023). "In the case of SPTBN1, data support that its expression levels are significantly down-regulated in various human cancers such as digestive tract cancer, pancreatic cancer, hepatocellular carcinoma, and lung cancer, reducing SPTBN1 expression has been linked to cancer progression." (PMID 35563422, 2022). "SPTBN1 can regulate the cell cycle and EMT through TGF-β and Wnt/β-catenin signaling pathways, thus regulating the proliferation and migration of hepatocellular carcinoma." (PMID 32516133, 2020). "We have reported that the absence of SPTBN1 in hepatocellular carcinoma can activate Wnt pathways by downregulating kallistatin, while kallistatin increases apoptosis in breast cancer cells by inhibiting miR-203 and enhancing SOCS3 levels via PKC-ERK signaling." (PMID 32516133, 2020). "In hepatocellular carcinoma (HCC), ATF3 cooperates with SPTBN1 and SMAD3 to inhibit STAT3 activity, thereby suppresses HCC development." (PMID 30455690, 2018). "However, the interaction between these two pathways in EOC EMT is still not clear, although suppression of SPTBN1 and SMAD3 promoted the transcription of STAT3 in hepatocellular carcinoma." (PMID 32516133, 2020).
liver cancer (11 papers, 2015 to 2024). An epithelial or non-epithelial malignant neoplasm that arises from the liver. "During the course of exploring the molecular mechanisms of SPTBN1 loss in the liver cancer formation, we performed microarray analysis in SNU-449 HCC cell line treated with SPTBN1 siRNA." (PMID 33754058, 2021). "We previously showed that disruptions in TGF-β signaling, coupled with loss of the SMAD adaptor SPTBN1, resulted in the spontaneous development of multiple tumors and a high incidence of liver cancer in human fibroblast and mouse models." (PMID 33457451, 2020). "We selected 14 translated tumor-mutated alleles for validation using SRM, including three genes (i.e., HNF1A, FAH and SPTBN1) that have been causally related to liver cancer." (PMID 26631547, 2015). "Moreover, loss of SPTBN1 expression induces liver cancer through downregulation of SOCS1 expression as well." (PMID 34527677, 2021). "In addition to the spontaneous liver cancer formation in mice with impaired SPTBN1, we also studied whether Sptbn1+/- mice are susceptible to the DDC induced malignancy in liver." (PMID 33754058, 2021). "SPTBN1 has recently been assigned a role as a therapeutic target for nonalcoholic steatohepatitis and liver cancer and thus detecting further highly expressed transcripts of this gene is important." (PMID 37267159, 2023). "We further analyzed infiltration of macrophages and Treg cells in liver cancers of mice as well as in human HCC tissues upon impairment of SPTBN1 by IHC." (PMID 33754058, 2021). "The results indicated that FASN was closely associated with liver cancer migration and invasion, and interacted with FSCN1, SIPA1, SPTBN1 and CD59." (PMID 32699531, 2020). "SMAD3 and its adaptor protein SPTBN1 are increasingly recognized as potent regulators of liver cancer stem cell development." (PMID 33457451, 2020). "Loss of SPTBN1 increases p65 protein stability via the inhibition of SOCS1 and enhances NF-κB activation, stimulating inflammatory responses and immune-suppressive conditions for the formation and progression of liver cancer." (PMID 33754058, 2021). "SPTBN1 may mediate liver cancer adhesive properties through an interaction with carcinoembryonic antigen related cell adhesion molecule 1-L and may have subsequent effects on the TGF-β-induced EMT signaling pathways." (PMID 32699531, 2020). "Indeed, SPTBN1 has been found to potentiate the expression of the Wnt inhibitor kallistatin in liver cancer." (PMID 32156068, 2020). "In the current study, silencing of FASN, FSCN1 or SPTBN1 expression in liver cancer cells led to changes in the mRNA expression of EMT-associated markers, E-cadherin, N-cadherin, vimentin and transcription factors Snail and Twist, and altered the protein expression of MMP-2 and MMP-9." (PMID 32699531, 2020). "β2-Spectrin (β2SP/SPTBN1, gene SPTBN1) is a key TGF-β/SMAD3/4 adaptor and transcriptional cofactor that regulates TGF-β signaling and can contribute to liver cancer development." (PMID 27248179, 2016). "The results showed that in the livers of mice fed with 0.1% DDC -containing diet for 3 months, 3 of 7 Sptbn1+/- mice developed liver cancer while there is no tumor visible in WT mice and Sptbn1+/- mice treated with NF-κB inhibitor JSH-23." (PMID 33754058, 2021). "SPTBN1 regulates molecular markers of EMT and the levels of the β-catenin target gene c-Myc via the Wnt signaling pathway, which mediates adhesion, migration and invasion of liver cancer." (PMID 32699531, 2020). "Knockdown of FASN in liver cancer reduced the expression of FSCN1, SIPA1, SPTBN1 and CD59." (PMID 32699531, 2020).
breast cancer (10 papers, 2014 to 2025). A primary or metastatic malignant neoplasm involving the breast. "Survival analysis showed that higher levels of BGN, FN1, COL11A1, and SPTBN1 are linked to poorer OS in patients with breast cancer." (PMID 40898538, 2025). "Higher expression levels of BGN, FN1, COL11A1, and SPTBN1 are linked to poorer overall survival in breast cancer patients is noticeable." (PMID 40898538, 2025). "In particular, in breast cancer, SPTBN1 has been reported to prevent the nuclear translocation of NF-κB p65, which impairs EMT process." (PMID 38069214, 2023). "Reviewing the literature, we found that SPTBN1 was downregulated in breast cancer cells and was a key regulator that inhibits EMT and breast cancer growth." (PMID 35075167, 2022). "AC093110.1 can adjust the expression of SPTBN1 in breast tumors as well as promote the proliferation and migration of breast cancer cells." (PMID 36212132, 2022). "Current research has confirmed that SPTBN1 has changed in breast cancer, but the specific mechanism and role of SPTBN1 in breast cancer need to be further clarified." (PMID 33390831, 2021). "Interestingly, a recent report by Wu and colleagues demonstrated that lower levels of SPTBN1 were correlated with shorter progression-free survival in breast cancer." (PMID 38069214, 2023). "SPTBN1 and GALNTL5 have also been implicated in breast cancer." (PMID 33672646, 2021). "In primary breast cancer tissues, the SPTBN1 expression was shown to be considerably downregulated as compared to normal, and it was identified to be a potent inhibitor of EMT and breast cancer progression." (PMID 36905477, 2023). "Further research found that SH3BGRL2 promotes breast cancer cell migration and invasion by inhibiting the expression of SPTAN1 and SPTBN1." (PMID 33390831, 2021).
osteoporosis (6 papers, 2016 to 2024). A condition of reduced bone mass, with decreased cortical thickness and a decrease in the number and size of the trabeculae of cancellous bone (but normal chemical composition), resulting in increased fracture incidence. "While our study implicates SPTBN1 in the context of osteoporosis primarily based on genome-wide association study (GWAS) data, we acknowledge existing literature supporting its involvement in bone health." (PMID 38683846, 2024). "To identify mechanisms of SPTBN1 in osteoporosis, we explored pathways related to SPTBN1 by STRING website and found that SPTBN1 may associate with TGF-β/Smad3 and STAT1/Cxcl9 signaling pathways." (PMID 33816505, 2021). "SPTBN1 is considered to be associated with the progression of osteoporosis, however, the specific functions and mechanisms remain unclear." (PMID 33816505, 2021). "Although βII-Spectrin (SPTBN1) has been reported to be involved in the development of various human cancers, the function and underlying molecular mechanisms of SPTBN1 in primary osteoporosis remain unclear." (PMID 33816505, 2021). "Among the 15 target genes of BMD and osteoporosis susceptibility loci, SPTBN1 is a molecular scaffolding protein which has been recognized as an osteoporosis susceptibility gene, and it shows co-expression with alpha-actinin binding and cell adhesion gene in the bone." (PMID 32269995, 2020). "This study suggested that SPTBN1 can be considered as a potential biomarker for the diagnosis and treatment of primary osteoporosis." (PMID 33816505, 2021). "The results showed that the expression of SPTBN1 was significantly downregulated in primary osteoporosis mice model compared with the control group." (PMID 33816505, 2021). "The expression of SPTBN1 was found to be significantly downregulated both in the senile osteoporosis group and postmenopausal osteoporosis group compared with corresponding control groups." (PMID 33816505, 2021). "Taken together, these results suggested that SPTBN1 suppressed primary osteoporosis by facilitating the proliferation, differentiation, and inhibition of apoptosis in osteoblasts via the TGF-β/Smad3 and STAT1/Cxcl9 pathways." (PMID 33816505, 2021). "As expected, overexpression of SPTBN1 reversed the effect of SPTBN1 silencing in the progression of primary osteoporosis both in vitro and in vivo." (PMID 33816505, 2021). "The results showed that overexpression of SPTBN1 significantly suppresses the development of primary osteoporosis by modulating VEGF, TGF-β/Smad3, and STAT1/Cxcl9 signaling pathways." (PMID 33816505, 2021). "The effect sizes of SNPs show the overexpression of SPTBN1 associated with decreased BMD level and increased osteoporosis risk." (PMID 32269995, 2020). "It was verified that SPTBN1 could be a novel therapeutic target for osteoporosis because SPTBN1 could facilitate the proliferative and differentiative capabilities of osteoblasts." (PMID 36444616, 2022). "This study, therefore, provided SPTBN1 as a novel therapeutic target for osteoporosis." (PMID 33816505, 2021). "The results extended the specific mechanisms of SPTBN1 in the progression of osteoporosis." (PMID 33816505, 2021). "A notable example is the SNPs located in the SPTBN1 coding region, where the SNP-association signals are significant and consistent across GWAS and eQTL datasets with PSMR = 3.15E-19 for BMD and PSMR = 2.20E-04 for osteoporosis." (PMID 32269995, 2020). "Finally, we found the expression of 15 target genes (SPTBN1, ASB16-AS1, SUPT3H-RUNX2, etc.)regulated by susceptibility loci, are associated with BMD and osteoporosis by integrating GWAS summary data with eQTL data." (PMID 32269995, 2020). "The regulation of SPTBN1 showed a possible pathogenic mechanism for both BMD and osteoporosis." (PMID 32269995, 2020). "Additionally, SPTBN1 could promote the proliferation, differentiation and repress the apoptosis of osteoblasts, thus protecting against primary osteoporosis." (PMID 36444616, 2022).
osteoporosis (continued). "Therefore, SPTBN1 may suppress primary osteoporosis of osteoblasts through Smad3/TGF-β and STAT1/Cxcl-9 signaling pathways." (PMID 33816505, 2021). "Besides, these results suggested that the effect of SPTBN1 in osteoporosis also might be mediated by the STAT1/Cxcl9 signaling pathway." (PMID 33816505, 2021). "Therefore, SPTBN1 may contribute to angiogenesis through regulating VEGF in osteoporosis." (PMID 33816505, 2021). "Thus, SPTBN1 may regulate osteoblast by TGF-β/Smad3 and STAT1/Cxcl9 signaling pathways in osteoporosis." (PMID 33816505, 2021). "However, the specific functions and mechanisms of SPTBN1 in osteoporosis have not been reported." (PMID 33816505, 2021).